TNF (tumor necrosis factor)
Diseases named in the same sentence as TNF in open-access papers (continued):
Sharing a sentence is not in itself a finding about the gene and the disease.
tumor (continued). "The levels of TNF-α, IFN-γ, and interleukin-6 in the tumor tissues of the GF/CuES group were 3.6-, 3.0-, and 5.02-fold those of the control group, respectively." (PMID 41424843, 2026). "While immunosuppressive factors such as CCL2, CXCL12, IL-4, and IL-10 sustain an immune-excluded TME, pro-inflammatory mediators like IFN-γ, TNF-α, and CXCL10 counteract these effects by promoting immune cell infiltration and tumor suppression." (PMID 40330466, 2025). "SASP molecules, like tumor necrosis factor alpha (TNFα) and intercellular adhesion molecule 1 (ICAM-1), promote the infiltration of natural killer (NK) cells into the tumor, where they execute their cytotoxic functions." (PMID 40723291, 2025). "For instance, cytokines such as IFN-γ, TGF-β, TNF-α, ECF and GM-CSF can promote tumor immune evasion by regulating the expression of PD-L156." (PMID 40861801, 2025). "With regard to M1/M2 polarization dynamics, M1 macrophages exert antitumor effects via IL-12/TNF-α secretion, whereas TREM2-driven M2 polarization promotes HCC progression by suppressing CD8+ T cell infiltration and enhancing tumor glycolysis." (PMID 41019983, 2025). "In contrast, 89% of the animals in the DMBA-induced group demonstrated a marked increase in tumor burden, characterized by structural disorganization, dense clusters of malignant cells, and elevated PCNA and TNF-α expression levels (p < 0.0001)." (PMID 40430573, 2025). "NK cells exhibit anti‐tumor potential by secretion of key cytokines such as IFN‐γ, TNF‐α, and GM‐CSF and by directly binding to tumor cells via their activating receptors to induce apoptosis." (PMID 40621806, 2025). "TNF‐α, another pro‐inflammatory cytokine secreted by adipocytes and SVF cells, has the potential to drive tumor progression and is increased in the plasma of obese individuals." (PMID 39496581, 2025). "Other tumor-derived factor like tumor necrosis factor-α (TNF-α) and interleukin-6 (IL-6) are also involved in MSC tumor-tropism by promoting endothelial adhesion and remodeling the cytoskeletal migration system." (PMID 39971901, 2025). "The development of HCC is strongly influenced by the tumor microenvironment (TME), characterized by elevated levels of pro-inflammatory cytokines (e.g., IL-6, TNF-α) and an enhanced immunosuppressive microenvironment contribute to HCC progression." (PMID 41422246, 2025). "Cytokines secreted by type 1 helper T cells (Th1), such as interleukin (IL)-2, IL-12, IL-18, interferon γ (IFN-γ), and tumor necrosis factor (TNF), participate in anti-tumor defense." (PMID 41561739, 2025). "CD4+ T cells are activated by tumor antigens presented by antigen-presenting cells (APCs) and produce cytokines such as IFN-γ and tumor necrosis factor-alpha (TNF-α), which in turn activate CD8+ CTLs and macrophages." (PMID 41007114, 2025). "CD4-positive T cells contribute to the inhibition of tumor growth by directly secreting cytokines such as IFN-γ and TNF, which suppress tumor angiogenesis." (PMID 41001043, 2025). "In addition, the reduction of adipose tissue may also affect the release of inflammatory factors such as interleukin-6 and tumor necrosis factor-α, thus improving the metabolic state of the body and the tumor microenvironment and increasing the sensitivity of treatment." (PMID 40904512, 2025). "In breast cancer, inflammatory cytokine networks, especially ILs and TNF, enhance immune infiltration and metastasis, with SPINK overexpression contributing to EGFR and Akt pathway activation, driving EMT and tumor progression." (PMID 40872585, 2025). "In the urethane-induced lung carcinogenic model, emodin reduces hypercoagulation and tumor lesions, accompanied by a decrease in N2 neutrophils and modulated cytokine profiles (IFN-γ, IL-12 up; IL-6, TNF-α, TGF-β1 down)." (PMID 40490812, 2025). "MAIT-derived IFN-γ has been shown to enhance NK cell anti-tumor activity, and MAIT cells can infiltrate tumors and promote pro-inflammatory microenvironments (e.g., IFN-γ and TNF-α production)." (PMID 41148807, 2025).
tumor (continued). "In the metastatic sensing stage, NK cells take up tumor‐derived vesicles, undergo glucometabolic remodeling, and exhibit reduced expression of NKG2D, CD107a, TNF‐α, and IFN‐γ." (PMID 40027151, 2025). "To investigate the clinical significance of METTL1-mediated codon-specific translation of TNF-α in PTC patients, we utilized PTC tumor tissues to validate the translational and clinical relevance of METTL1, WDR4, and TNF-α interactions." (PMID 40360483, 2025). "Among these, IL-1β, IL2, IL6 play critical roles in activating immune cells and amplifying proinflammation responses, while TNFα and IL27 can directly inhibit the growth of tumor cells." (PMID 40046011, 2025). "Mechanistic studies revealed that Butein markedly downregulated the protein and mRNA expression of TWEAK, FN14, and TRAF1/2 in tumor tissue, and decreased serum levels of NF-κB-related inflammatory factors, including IL-1β, IL-6, IFN-γ, and TNF-α." (PMID 41458609, 2025). "TAM-secreted cytokines such as IL-1β, IL-8, TNF-α, and TGF-β promote EMT in cancer cells, leading to disrupted intercellular junctions and accelerated tumor cell movement." (PMID 41417432, 2025). "These YGP-activated monocytes exert direct cytotoxicity against tumor cells in vitro, and systemic YGP treatment increases the levels of inflammatory mediators such as TNF-α, M-CSF, and CCL2 in the lungs." (PMID 41163402, 2025). "Intriguingly, these cells can exert anti-tumor effects by releasing mediators such as CXCL9, CXCL10, TNF-α, granzyme, cationic proteins, in melanoma, CRC, and HCC." (PMID 40380196, 2025). "Those cells are induced to transfer into TNF/iNOS-producing DCs (Tip-DCs) in the inflammatory environment and have been proven to produce NO for CD8+ T cells to kill tumor cells in the murine model." (PMID 40297580, 2025). "Aging immune cells also promote tumor metabolic reprogramming via cytokines and secreted factors: Senescent immune or stromal cells secrete pro-inflammatory SASP factors (e.g., IL-6, IL-8, TNF-α, CXCL1), activating STAT3 and NF-κB pathways in tumor cells." (PMID 40881346, 2025). "Pro-inflammatory cytokines, such as IFN-γ, TNF-α, and IL-2, primarily secreted by CD8+ cytotoxic T cells and NK cells, are pivotal in mediating tumor-immune defense." (PMID 40868199, 2025). "In tumor-bearing mice, Lingzhi extract (GLE; 200–400 mg/kg) was known to upregulate cytokines such as IFN-γ, IL-2, and TNF-α, thus producing T cell-mediated antitumor immunity." (PMID 40733125, 2025). "In TNBC, ATM inhibition increased MHC-I expression through a c-Jun/TNF-α/p-STAT1 axis, augmented CD8+ T-cell infiltration and cytotoxicity, slowed tumor growth, and sensitized tumors to PD-1 blockade and radiotherapy in vivo." (PMID 41293269, 2025). "CM exosomes display notable anti-inflammatory activity by reducing pro-inflammatory cytokines such as TNF-α, TGF-β1, IL-1β, and NF-κB in tumor cells." (PMID 41007307, 2025). "MCs contribute to the angiogenic switch via secretion of the mentioned VEGF, matrix metalloproteinases (MMPs), TNF-α, and IL-8, TNF-α, and IL-8, facilitating neovascularization and tumor expansion." (PMID 40871387, 2025). "Flow cytometric analysis revealed more cytotoxic CD8+ T-cells with higher IFNγ, TNFα, and IL2 expression—indicative of a more effective anti-tumor immune response (SF." (PMID 40951290, 2025). "TNF-α and IFN-γ are pivotal immune cytokines that directly inhibit tumor cell growth, enhance immune cell cytotoxic function, and modify the TME to facilitate immune cell infiltration and attack." (PMID 40104638, 2025). "The traditional M1/M2 paradigm suggests that M1 macrophages, induced by IFN-γ, TNF-α, and TLR signaling, promote anti-tumor immunity through the production of pro-inflammatory cytokines and reactive oxygen species." (PMID 40330466, 2025).
tumor (continued). "These macrophages secrete proinflammatory and protumorigenic mediators, such as IL‐6, TNF‐α, and TGF‐β, which not only promote tumor cell proliferation and metastasis but also inhibit the effector functions of CD8+ T cells." (PMID 41267926, 2025). "To date, tumor-directed delivery of IL-15/4-1BBL (scFv anti-FAP), IL-2/TNF (scFv anti-EDA) and IL-2/IL-12 (scFv-Fc anti-CD30, LAIR2), has shown significant therapeutic effects in preclinical tumor mouse models." (PMID 40370435, 2025). "For example, TAM-derived IL-6, TNF-α and STAT3 signaling were believed to aggravate inflammation of TME and accelerate tumor advancement in PDAC and HCC." (PMID 40380196, 2025). "After the mice were sacrificed, T cells and macrophages were analyzed using flow cytometry; dual co-blockade increased significantly the percentage of M1 macrophages in the tumor microenvironment, followed by an increase in expression of CD86+ and TNFα+." (PMID 41096863, 2025). "ELISA quantification of tumor lysates further revealed pronounced upregulation of IFN-γ and TNF-α in the VNPSORT-IL2 + US group." (PMID 41041051, 2025). "CD4+ helper T cells augment this response by producing interleukin-2, tumor necrosis factor-α, and interferon-γ, which promote CTL function, enhance macrophage and NK cell activity, and increase tumor antigen presentation." (PMID 41194932, 2025). "The pro-inflammatory cytokines TNF-α, IFN-γ, and IL-1β were significantly elevated following tumor induction." (PMID 41301523, 2025). "This nanoparticle enhances tumor immunotherapy by disrupting mitochondrial function and activating CD4+ and CD8+ T cells, thereby increasing IL-2 and TNF-α expression, and significantly inhibiting tumor growth." (PMID 39742149, 2025). "They employed engineered EcN harboring a blue light-responsive genetic circuit that triggers lysis and release of TNF-related TRAIL upon blue light exposure, enabling targeted tumor cell killing." (PMID 41155984, 2025). "These cells release tumor necrosis factor (TNF)-α and CC motif chemokine ligand 3 (CCL3, formerly known as macrophage inflammatory protein-1α, MIP-1α), exerting suppressive effects on the tumor growth." (PMID 40136347, 2025). "Taken together, these data indicate that Ad5NULL-A20 CD16-EGFRscfvs is a potent activator of NK cells inducing cytotoxicity and release of TNF-α and IFN-γ resulting in NK cell-induced tumor cell death." (PMID 40741595, 2025). "Squ, squamocin; APS, astragalus polysaccharides; TME, tumor microenvironment; m DC, mature dendritic cells; im DC, immature dendritic cells; GSH, glutathione; GSSG, glutathione disulfide; IFN, interferon; TNF, tumor necrosis factor." (PMID 40688661, 2025). "We also observed a higher inflammatory response hallmark observed following the addition of degarelix to olaparib, including TNFα and JAK-STAT signalling, including within tumour epithelial fractions." (PMID 40358364, 2025). "This activation results in elevated tumor necrosis factor-α (TNF-α) levels and increased expression of matrix metalloproteinases (MMPs), contributing to ECM disintegration and accelerating skin aging." (PMID 40822678, 2025). "Another in vitro study revealed that NE treatment with a cocktail consisting of TNF‐α, CD40 agonist, and a tumor‐specific antibody showed increased tumor‐killing activity in human tumor cells through ADCC." (PMID 39801750, 2025). "This reduction led to an increase in the infiltration of pro-inflammatory, tumor-fighting CD8+ T cells producing TNFα and IFNγ, suggesting that tryptophan metabolism by Lactobacillus can modulate immune responses in PDAC, potentially affecting tumor growth." (PMID 40927726, 2025). "Given that TNF-α signaling amplifies IL-6 and IL-8 secretion in the CRC TME, fostering apt conditions for tumor invasion, it is imperative to evaluate OC’s capacity to attenuate this cytokine axis." (PMID 40564985, 2025).
tumor (continued). "Lymphocytes control tumor growth by secreting cytokines such as interferon-γ (IFN-γ) and tumor necrosis factor-α (TNF-α) which interact with each other." (PMID 40297178, 2025). "These chemokines are primarily secreted by monocytes, endothelial cells, fibroblasts, and tumor cells in response to IFN-γ, with their secretion being synergistically enhanced by tumor necrosis factor alpha (TNFα)." (PMID 40447617, 2025). "When coincubated with tumor cells, γδ CAR-T cells presented increased expression levels of CD69, TNF-α and granzyme B." (PMID 39939816, 2025). "Specifically, IFNγ and TNFα were identified as key upstream regulators that dictate the activation status of eosinophils facilitating CD4+ and CD8+ T cell infiltration and anti-tumor immunity." (PMID 40050933, 2025). "TAMs directly or indirectly affect tumor vasculature and participate in angiogenesis by secreting pro-angiogenic factors and inflammatory factors, including VEGF-A, MMP, EGF, TGF-β, and TNF-α." (PMID 40131539, 2025). "Thus, therapeutically shifting the balance from T celllow/M2 macrophagehigh/BL towards T cellhigh/macrophagelow/CLA-like state through inhibition of TNF-α with GEM chemotherapy may provide a valuable strategy to enhance anti-tumor immunity and treatment response in PDAC." (PMID 39762215, 2025). "These T cells exhibit greater infiltration into the tumor, higher expression of pro-inflammatory cytokines like IFN-γ and TNF-α, and improved tumor control." (PMID 40330466, 2025). "Pro-tumorigenic cytokines include IL-6, TGF-β, vascular endothelial growth factor (VEGF), and IL-10, while anti-tumor cytokines include IFN-γ, tumor necrosis factor-α (TNF-α), and IL-12." (PMID 40227644, 2025). "Our results revealed a predominantly pro-inflammatory tumor microenvironment, driven by cytokines such as CXCL8, IL-6, and TNF-α, which create a favorable niche for tumor growth." (PMID 40895532, 2025). "Our in vitro studies revealed that uPA–/– CD8+ T cells exhibited enhanced tumor-killing activity through the secretion of GzmB, IFN-γ, and TNF-α." (PMID 40959092, 2025). "Its induction by tumor-promoting cytokines, including bone morphogenetic protein 2 (BMP2) and tumor necrosis factor-α (TNF-α), further highlights its role in cell invasion and metastasis." (PMID 41011506, 2025). "Given the increased expression of GzmB, IFNγ and TNFα by M002-treated CD4+ T cells, and their tumor reactivity, we next determined if these CD4+ T cells were capable of mediating killing of tumor cells beyond their conventional helper activity." (PMID 39885128, 2025). "The expression levels of PD-L1 and PD-1 were significantly elevated in tumor tissues, whereas CD69, IFN-γ, and TNF-α levels were markedly reduced (all p < 0.05)." (PMID 41445633, 2025). "We next quantified pathway-level activity for eight tumour-relevant processes, including epithelial–mesenchymal transition (EMT), angiogenesis, hypoxia, inflammatory response, IL6-JAK-STAT3 signalling, TNFα-NFκB signalling, and interferon responses." (PMID 41007424, 2025). "ELISA revealed elevated TNF-α and INF-γ levels in tumor tissues within the DIFP-FA + US + PD-1 group." (PMID 40104638, 2025). "We also conducted ELISA of the supernatant of the BMDCs to further identify elevated excretion of inflammatory cytokines including tumor necrosis factor-α (TNF-α) and IFN-γ, collectively demonstrating the oxidative inflammation within the tumor cells." (PMID 40739587, 2025). "We have previously shown that NK cells directly kill CSCs or inhibit tumor growth by differentiating tumors via secreted factors, especially IFN-γ and TNF-α." (PMID 39851518, 2025). "NK cells eliminate tumor cells via direct lysis and modulate the adaptive immune system through cytokines such as IFN-γ and TNF-α." (PMID 41244711, 2025). "M1 are stimulated by TNF-α and IFN-γ to produce pro-inflammatory cytokines such as IL-1, IL-6, IL-12, IL-23, CXCL-10 and TNFα and in that way contribute to destroying tumor cells in the TME." (PMID 40376304, 2025).
tumor (continued). "Mice treated with the hydrogel exhibited not only reduced hypoxic burden but also increased IFN-γ and TNF-α secretion from macrophages in the blood, spleen, and TME, culminating in significantly suppressed tumor growth." (PMID 41294574, 2025). "GO analysis also revealed activation of the tumor necrosis factor (TNF) and Janus kinase (JAK)-STAT signaling pathways in PC9-BM cells and in tumor cells with high LCN2 expression in clinical BM patient samples." (PMID 41436606, 2025). "In contrast, male enrichment of pathways involved in tumor-supportive inflammatory activity (TGF beta signaling and TNF alpha signaling via NFKB) were observed in grade II-III TAM-MGs." (PMID 38895459, 2025). "In contrast, CD8_Teff cells maintained anti-tumor activity by secreting IFN-γ and TNF-α, showing a positive correlation with immune therapy response." (PMID 40740771, 2025). "Exhausted T cells show increased expression of inhibitory receptors, including CTLA-4 and PD-1, and reduced production of effector cytokines, such as IL-2, tumor necrosis factor (TNF-α), and IFN-γ, further weakening the immune response against the tumor." (PMID 40006624, 2025). "CD8+T cells, which secrete TNF-α and IFN-γ are essential effectors involved in tumor cell elimination, whereas CD4+T cells are pivotal in orchestrating the overall antitumor response." (PMID 40670983, 2025). "This strategy has been successfully applied to enhance tumor targeting in vivo, where SPION-coated EVs loaded with TNF-α demonstrated potent anti-tumor activity under an external magnetic field." (PMID 40284522, 2025). "Further mechanistic exploration revealed that TNF‐α+ Tregs regulate the IL‐13/STAT3 signalling axis, inhibiting tumour stemness and progression." (PMID 40665579, 2025). "This modification led to increased secretion of pro-inflammatory cytokines TNF-α and IFN-γ, and promoted greater T-cell expansion, thereby augmenting the anti-tumor efficacy of the redirected T cells." (PMID 40643499, 2025). "The results showed that NOS and Arg-1 activity in Lnk–/– tumor PMN-MDSCs were decreased, while the expression of IFN-γ and TNF-α was increased." (PMID 40796725, 2025). "Th1 secretes TNF-α and IFN-γ cytokines that enhance and stimulate CD8+ cells, and macrophages (anti-tumor phenotype, M1)." (PMID 41369383, 2025). "Neutrophil survival facilitated by GM-CSF leads to the secretion of various pro-inflammatory and angiogenic factors, such as IL-8, VEGF-A, TNF-α, and MMP-9, all contributing to tumor progression and angiogenesis." (PMID 40150133, 2025). "CD8+ T cells recognize tumor antigens via TCRs, releasing perforin and granzyme to kill cancer cells and secreting IFN-γ and TNF-α to inhibit tumor growth." (PMID 40443668, 2025). "Biological evidence highlights the involvement of pro-inflammatory cytokines (IL-6, IL-1β, TNF-α), NF-κB signaling, and activation of the tryptophan–kynurenine pathway (IDO), suggesting a link between tumor-related processes and mood alterations." (PMID 41514529, 2025). "The selection of specific cytokines (TNF-α, IFN-γ, IL-12, and IL-6) for assessing T-cell-mediated immune activation was guided by their established roles in anti-tumor immunity." (PMID 40722845, 2025). "Memory B cells in an inflamed tumor microenvironment may actively participate in anti-tumor immunity and can function as potent antigen-presenting cells that restimulate T cells and secrete pro-inflammatory cytokines (e.g., TNFα, IL-6, IFN-γ) to recruit and activate other immune effectors." (PMID 41222706, 2025). "The peptides AK and GK competitively bound to the receptor to modulate the TNF/TNFR-signaling cascade and alter the tumor microenvironment." (PMID 39860044, 2025). "Deleting Tak1 impaired in vivo tumor growth, enhanced α-PD-1 immunotherapy, and lead to durable anti-tumor memory, dependent on CD8 T cells and intact TNF-α signaling." (PMID 41102176, 2025).